CDKN2A (cyclin dependent kinase inhibitor 2A)
Diseases named in the same sentence as CDKN2A in open-access papers (continued):
Sharing a sentence is not in itself a finding about the gene and the disease.
colorectal cancer (continued). "Further experiments revealed that silencing CDKN2A markedly decreased the mRNA levels of the phosphofructokinase genes PFKL and PFKM in colorectal cancer cell lines." (PMID 38888512, 2024). "In particular, genes CDKN2A and TIMP1 have been shown to be closely related to the prognosis of colorectal cancer." (PMID 39120548, 2024). "Following CDKN2A knockout, we detected an upregulation of the copper uptake gene SLC31A2 and a downregulation of the copper efflux gene ATP7B in colorectal cancer cell lines." (PMID 38888512, 2024). "For example, analyses of MLH1 and CDKN2A(p16) methylation combined with the CIMP status exhibit clinical and prognostic value in colorectal cancer." (PMID 32806509, 2020). "We obtained 401 colorectal cancer specimens and successfully quantified DNA methylation in eight CIMP-specific gene promoters (CACNA1G, CDKN2A, CRABP1, IGF2, MLH1, NEUROG1, RUNX3, and SOCS1) using MethyLight technology." (PMID 31690257, 2019). "In the present study, we evaluated the methylation of the CDH1, DAPK, CDKN2A, and TIMP2 genes in five colorectal cancer patients from Manaus, the capital of the Amazon state in Brazil." (PMID 26363785, 2015). "Here, we analyzed the methylation pattern from five colorectal cancer patients from the Amazon state in Brazil for four tumor suppressor genes, viz.: DAPK, CDH1, CDKN2A, and TIMP2 by employing a polymerase chain reaction (PCR) specific to methylation." (PMID 26363785, 2015). "We analyzed 90 samples of surgically resected colorectal cancer tissues for APC and CDKN2A promoter methylation using methylation sensitive-high resolution melting (MS-HRM) and pyrosequencing." (PMID 23326336, 2013). "We obtained 920 colorectal cancer specimens and quantified DNA methylation in the 8 CIMP-specific gene promoters (CACNA1G, CDKN2A, CRABP1, IGF2, MLH1, NEUROG1, RUNX3 and SOCS1) by MethyLight technology." (PMID 17474983, 2007). "Additionally, two genes, CDKN2A and TIMP1, stand out for their extensive study in colorectal cancer." (PMID 39120548, 2024). "CDKN2A, CMTM8, ILK, and their co-expression genes were enriched in the following pathways: ILK pathway, TGF-β pathway, epithelial to mesenchymal transition in colorectal cancer, integrin-mediated cell adhesion, signaling by Notch, and so on." (PMID 35429970, 2022). "It was found that the mutation frequency of each regulator is relatively low, of which ATP7A showed the highest mutation rate, followed by ATP7B and LIPT1, while FDX1, CDKN2A, SLC31A1, and GCSH showed no mutation in all colorectal cancer tissues." (PMID 36248908, 2022). "CDKN2A and AKR1C1 were established as novel ferroptosis-related signatures that could effectively predict colorectal cancer prognosis." (PMID 36275721, 2022). "Recent studies conducted on colon cancer suggested that both the CDKN2A gene methylation and the lack of CDKN2A expression were not related to colorectal cancer-specific passings." (PMID 33896386, 2021). "CDKN2A is one of the most frequently hypermethylated genes in The Cancer Genome Atlas, and numerous clinical studies show a negative correlation between CDKN2A methylation and expression in colorectal cancer." (PMID 27170255, 2016). "The aim of this study is to analyse CDKN2A methylation using pyrosequencing on a large cohort of colorectal cancers and corresponding non-neoplastic tissues." (PMID 22925370, 2012). "Primary colorectal cancers and matched non-neoplastic tissues from 432 patients underwent CDKN2A methylation analysis by pyrosequencing (PyroMarkQ96)." (PMID 22925370, 2012).
colorectal cancer (continued). "Our study revealed that the group with high CDKN2A expression had a much greater TIDE, Dysfunction, and CD8 scores than the group with low CDKN2A expression, implying that immunotherapy is more effective in treating colorectal cancers with high CDKN2A expression." (PMID 37950153, 2023). "Fusobacterium nucleatum, a gram-negative anaerobic bacillus, is mainly associated with colorectal cancer patients positive for the CpG island methylator phenotype, although hypermethylation in genes such as MLH1, CDKN2A, MTSS1, RBM38, PKD1, PTPRT, and EYA4 has also been described." (PMID 37614819, 2023). "Furthermore, different genes are hypermethylated in cancers such as CDKN2A, hMLH1, and APC in colorectal cancer (CRC); p16INKa, RB1, and VHL1 in renal cell carcinoma; TET2, DNMT3B, IDH1, BRAF, and MYC in prostate cancer; and MGMT in colon, lung, lymphoid, and other tumors." (PMID 35327559, 2022). "Additionally, we highlight the negative and independent prognostic effect of CDKN2A methylation on prognosis in patients with colorectal cancer using pyrosequencing." (PMID 22925370, 2012). "Although NEUROG1 and CDKN2A have shown to be methylated in colorectal cancers, CSMD1-3 methylation did not correlate with NEUROG1 (p = 0.432, R = .1081) or CDKN2A (p = 0.537, R = .08488) methylation, though these two markers did positively correlate with each other (p<0.01)." (PMID 23505554, 2013). "Utilizing MethyLight technology (real-time PCR), we quantified DNA methylation in 8 CIMP-specific promoters {CACNA1G, CDKN2A (p16), CRABP1, IGF2, MLH1, NEUROG1, RUNX3 and SOCS1} in 758 non-MSI-high colorectal cancers obtained from two large prospective cohorts." (PMID 17474983, 2007).
meningioma (121 papers, 2007 to 2026). A generally slow growing tumor attached to the dura mater. "Loss of NF2 and CDKN2A/CDKN2B is common in higher-grade meningiomas and promotes progression in preclinical models." (PMID 41545592, 2026). "Even the heterozygous deletion of CDKN2A/B is associated with poor outcomes, and meningiomas with increased mRNA expression of CDKN2A/B are also linked to worse prognosis with significant resistance to CDK inhibitors." (PMID 40075786, 2025). "Potential molecular mechanisms of MT include chromosomal abnormalities (Chromosome 22q deletion, NF2 gene mutation, loss of chromosome 1p), genomic alterations (FOXM1, CDKN2A/B and TERTp), and meningioma cancer stem cells." (PMID 39991581, 2025). "In this study, homozygous CDKN2A/B loss was observed in a single grade 3 meningioma, while all histologically low-grade tumors retained intact CDKN2A/B and TERT loci." (PMID 40951339, 2025). "Particularly, any meningioma with CDKN2A/B homozygous deletion or TERT promoter mutation should be diagnosed as WHO grade 3, regardless of histological criteria of anaplasia." (PMID 39991581, 2025). "According to genetic analysis, TERTp mutation and homozygous CDKN2A/B loss should be searched for in cases of aggressive atypical meningiomas and meningiomas with borderline grade 2–3 histology." (PMID 40423252, 2025). "As a result, we cannot guarantee the exclusion of the group classified as having grade 3 anaplastic meningioma in 2021 based on TERT mutation or CDKN2A/B homozygous deletion." (PMID 38369575, 2024). "One grade 2 meningioma showed regional CDKN2A loss by FISH and variable MTAP expression under different IHC conditions." (PMID 39409918, 2024). "The WHO 2021 classification has proposed some specific molecular markers to be associated with grade 3 meningiomas (e.g., homozygous deletion of CDKN2A/B) because they confer a poorer prognosis." (PMID 38785832, 2024). "The two meningiomas with partial and complete loss of CDKN2A, also showed partial and complete loss of p16 expression, respectively." (PMID 39409918, 2024). "A heterozygous deletion of cyclin-dependent kinase inhibitors A and B (CDKN2A/B) was also associated with a shorter time of meningioma recurrence, and it importantly correlates with shorter RFS in surgically resected atypical meningiomas." (PMID 39202270, 2024). "One grade 3 meningioma that demonstrated homozygous CDKN2A loss by FISH also showed loss of MTAP expression by IHC." (PMID 39409918, 2024). "Cyclin-dependent kinase inhibitor 2A/B (CDKN2A/B) loss is a key factor in diagnosing meningiomas as Central Nervous System (CNS) WHO grade 3 tumors." (PMID 39409918, 2024). "Recently, it has been suggested that MTAP expression by IHC can be utilized as a surrogate marker for CDKN2A/B loss in meningiomas." (PMID 39409918, 2024). "FISH studies revealed one grade 3 meningioma with homozygous CDKN2A loss (2%) and one grade 2 meningioma with focal CDKN2A loss (2%)." (PMID 39409918, 2024). "Even heterozygous CDKN2A/B deletions were associated with an increased risk of meningioma progression compared with wild-type, too (HR = 6.4, 95% CI = 4.0–10.5, p < 0.00001)." (PMID 38017560, 2023). "As such, the revised definition of anaplastic meningioma in the 2021 WHO Classification of Central Nervous System Tumors now includes any meningioma that harbors TERT promoter mutation or CDKN2A homozygous deletion." (PMID 36723772, 2023). "In the cohort of only CDKN2A intact/wt meningiomas, all meningiomas with PIK3CA or POLR2A mutations were CDKN2Alow cases, whereas the only meningioma with an ARID1A mutation was CDKN2Ahigh." (PMID 37093270, 2023). "Recently, it was shown that even heterozygous loss of CDKN2A/B greatly accelerates recurrence in aggressive meningioma." (PMID 37686527, 2023).
meningioma (continued). "Regarding PFS, the pooled HR of 7.3 (95% CI 5.4–9.9, p < 0.00001) confirms the significant findings of the single-stage meta-analysis that any type of CDKN2A/B deletions are strongly associated with shortened time to meningioma progression." (PMID 38017560, 2023). "For morphologically grade 2 meningiomas, identification of an underlying CDKN2A homozygous deletion would now lead to an integrated CNS WHO grade 3 designation that has treatment implications including clinical trial eligibility." (PMID 36723772, 2023). "In meningiomas, alterations of CDKN2A/B are more common in higher grade tumors and are associated with high clinical recurrence." (PMID 37898750, 2023). "MTAP immunohistochemistry has been described as a surrogate marker for homozygous CDKN2A loss correlating with higher graded meningiomas." (PMID 38023177, 2023). "Homozygous CDKN2A/B deletion was strongly associated with an increased risk of meningioma progression compared with wild-type (HR = 8.4, 95% CI = 5.9–12.1, p < 0.00001)." (PMID 38017560, 2023). "Although CDKN2A/B deletions have been implicated in many different cancers, including meningiomas, how these changes correlate with mRNA expression and outcome have yielded paradoxical findings." (PMID 37093270, 2023). "The loss of several chromosomal regions, including NF2 and CDKN2A, which is associated with aggressive meningiomas, was considered a significant driver event for malignant progression." (PMID 38073632, 2023). "Both hetero- or homozygous CDKN2A/B deletions were significantly associated with shortened time to meningioma progression." (PMID 38017560, 2023). "Additional TERT promoter mutation and homozygous CDKN2A/B loss have similarly been linked to more aggressive meningiomas In contrast, homozygous CDKN2A/B loss, TERT promoter mutations or alterations in BAP1 are associated with more aggressive clinical courses." (PMID 36641486, 2023). "In summary, we demonstrate meningiomas harboring CDKN2A homozygous deletion or truncating mutation exhibit loss of p16 expression by immunohistochemistry." (PMID 36723772, 2023). "For example, meningiomas with a telomerase reverse transcriptase (TERT) promoter mutation or a homozygous deletion of CDKN2A and/or CDKN2B are classified as WHO grade 3." (PMID 37675219, 2023). "One-stage meta-analysis showed that hetero- (HR: 5.5, 95% CI 4.0–7.6, p < 0.00001) and homozygous CDKN2A/B deletions (HR: 8.4, 95% CI 6.4–11.0, p < 0.00001) are significantly associated with shortened time to meningioma progression." (PMID 38017560, 2023). "Homozygous CDKN2A/B deletion has been associated with an increased risk of recurrence in meningiomas." (PMID 38017560, 2023). "Nearly all meningiomas with TERTp mutations were found in the more aggressive epigenetic group B classes and 70% of all meningiomas with CDKN2A/B deletion belonged to the MC mal class." (PMID 36840836, 2023). "In case of aggressive atypical meningiomas and meningiomas with borderline grades 2–3 histopathology, genetic analyses have revealed that TERTp mutation and homozygous CDKN2A/B loss should be looked for and when present indicate a grade 3 tumour." (PMID 35879477, 2022). "The case that was classified into Mal MC (Patient 11) showed multiple losses including 1p, 8p, 10, 14, 22q, as well as NF2 truncating mutation and homozygous deletion of CDKN2A/B, alterations commonly seen in atypical and anaplastic meningiomas." (PMID 35440040, 2022). "This is because the histologic grading criteria alone are unable to stratify prognosis in meningioma, and TERTp mutation and CDKN2A/B homozygous deletion are independent prognostic markers in grade 1 and grade 2 meningiomas." (PMID 36264940, 2022). "Mutations in SMARCE1, BAP1, KLF4/TRAF7, TERT promoter, and CDKN2A/B deletion, H3K27me3 loss and methylation profiling are now officially associated with the classification and grading of meningiomas." (PMID 34846640, 2022).
meningioma (continued). "One case had the loss of one or two copies of CDKN2A/B, 11 meningiomas had the loss of 18q, while these genetic alterations co-occurred in 2 cases." (PMID 33670055, 2021). "Mutations in the TERT promoter have been associated with worse prognosis and decreased survival rates in grade II and III meningiomas, and CDKN2A mutation or gene deletion has been associated with meningioma recurrence." (PMID 34300316, 2021). "Such an adverse outcome is in line with the reported association between CDKN2A/B homozygous deletion and higher recurrence risk of meningiomas." (PMID 33670055, 2021). "In relation to the different methylation classes reported to independently stratify for risk of recurrence among meningioma, CDKN2A/B homozygous deletion was observed only in the methylation classes “intermediate” (n = 6; 23%) or “malignant” (n = 20; 77%)." (PMID 32642869, 2020). "Consistent with previous studies, homozygous deletion of CDKN2A/B was found mainly in meningiomas graded as WHO grade II or III which underlines a potential role in the malignant transformation of meningiomas." (PMID 32642869, 2020). "Known mutations in genes including AKT1, TRRAF7, KLF4, and CDKN2A predispose to meningioma, including high grade meningiomas in the human WHO grading scheme." (PMID 31788444, 2019). "HOXA-AS2 has been shown to mediate transcriptional repression of the tumor suppressor gene CDKN2A (p16INK4A), deletion of which is associated with poor meningioma survival." (PMID 30202034, 2018). "Interestingly, three grade 2 meningiomas displayed hemizygous CDKN2A/B loss, a finding that has been linked to poor outcomes in some studies." (PMID 40951339, 2025). "Besides 1p deletion, losses of chromosome 6q, 10, 17q and 18q, mutations of the TERT promoter or homozygous deletions of CDKN2A/B are described to influence the clinical course in meningioma patients." (PMID 39775316, 2025). "Therefore, it is important to identify meningiomas with CDKN2A/B homozygous loss for the accurate risk stratification of patients." (PMID 39409918, 2024). "The update in 2021 included molecular factors that significantly shorten survival and increase recurrence, such as meningiomas with a telomerase reverse transcriptase (TERT) promoter mutation or homozygous deletions in the cell cycle regulator genes CDKN2A and/or CDKN2B." (PMID 39796674, 2024). "Anaplastic meningioma with CDKN2A loss has a poor prognosis, even in re-radiation." (PMID 39358739, 2024). "Additionally, heterozygous loss, mutations, and promoter methylation of CDKN2A were strongly associated with recurrent meningiomas and a high Ki-67 index." (PMID 39358739, 2024). "In our study, MTAP expression showed 100% (41/41) specificity at the 1:100 dilution and 95% (39/41) specificity at the 1:1200 dilution for identifying meningiomas with intact CDKN2A status and 100% (2/2) sensitivity for detecting meningiomas with CDKN2A homozygous loss." (PMID 39409918, 2024). "MG3 and MG4 meningiomas were enriched for prognostically unfavorable alterations including TERTp mutation and homozygous loss of CDKN2A/B, in addition to novel somatic mutations in KDM6A, CHD2, and PTEN, and these tumors had a significantly higher degree of chromosomal instability." (PMID 38695575, 2024). "Therefore, a reliable IHC-based assay to detect CDKN2A/B homozygous loss in meningiomas will improve clinical practice by reducing the cost and turn-around time of diagnosing and grading meningiomas according to the WHO criteria." (PMID 39409918, 2024). "The 2021 WHO Classification includes molecular features, that is, pTERT mutation and CDKN2A/B HoDe, in meningioma grading for the first time, thus allowing the identification of some meningiomas devoid of malignant histological features but prone to a higher recurrence risk." (PMID 37296907, 2023).